BHLHE40 (basic helix-loop-helix family member e40)
Diseases named in the same sentence as BHLHE40 in open-access papers (continued):
Sharing a sentence is not in itself a finding about the gene and the disease.
pancreatic cancer (continued). "In pancreatic cancer, the observed higher BHLHE40 levels in pancreatic cancer compared with the low levels in non-tumor tissues, and the low expression of BHLHE40 is associated with a good prognosis of pancreatic cancer." (PMID 37773521, 2023). "In a nutshell, hsa-miR-15a-5p might be negatively regulated in pancreatic cancer by targeting BHLHE40." (PMID 37773521, 2023). "Silencing of BHLHE40 could inhibit proliferation, invasion, and apoptosis of pancreatic cancer in vitro and in vivo, implying that BHLHE40 is expected to be a potential therapeutic target for pancreatic cancer." (PMID 37773521, 2023). "Moreover, we analyzed the correlation between BHLHE40 expression and immune activation was analyzed to show that BHLHE40 expression in pancreatic cancer was closely related to immunosuppression." (PMID 37773521, 2023). "Hereby, we investigated the pro-oncogenic role of BHLHE40 in the pancreatic cancer microenvironment by bioinformatics analysis and cell biology experiments and determined that the expression of BHLHE40 was obviously elevated in pancreatic cancer tissues than in adjacent normal tissues." (PMID 37773521, 2023). "BHLHE40 is primarily a transcriptional regulator that is often deleted or downregulated in cancer, including Burkitt’s lymphoma, osteosarcoma, non-small cell lung cancer and in pancreatic cancer." (PMID 32577154, 2020). "Together, these reports suggest a tumor suppressive role of nuclear BHLHE40 in pancreatic cancer." (PMID 32577154, 2020). "Furthermore, the elevated expression of BHLHE40 was correlated with hypoxia activation, increased metastatic potential, and poor prognosis of various cancer types including hepatocellular carcinoma, pancreatic cancer, and invasive breast cancer." (PMID 33602983, 2021). "Further studies have shown that BHLHE40 regulates the transcription of element-binding factor 1 (SREBF1), and that the bHLHE40-SREBF1 axis regulates the protection of pancreatic cancer cells from ferroptosis." (PMID 40959280, 2025). "Ultimately, combining the relationship between lncRNAs and survival of pancreatic cancer patients, we found that FGD5-AS1 was most likely to act as upstream of BHLHE40." (PMID 37773521, 2023). "Lastly, we identified the biological function of BHLHE40 and revealed that the FGD5-AS1/miR-15a-5p axis was the most probable lncRNA-related pathway in pancreatic cancer." (PMID 37773521, 2023). "Specifically, to validate the activation of the FGD5-AS1/miR-15a-5p/BHLHE40 axis in pancreatic cancer in vivo, fluorescence in situ hybridization (FISH) was employed to characterize the expression of FGD5-AS1, miR-15a-5p and BHLHE40 and co-localization among these members in the tumor tissues." (PMID 37773521, 2023). "High expression of BHLHE40 is significantly correlated with the activation of a hypoxia-response pathway, elevated metastatic potential, and a poor prognosis in many tumours, such as HCC, pancreatic cancer, and invasive breast cancer." (PMID 35109839, 2022). "In this study, higher levels of BHLHE40 was observed in pancreatic carcinoma compared to low levels in non-tumor tissue; however, it was noted that the increased BHLHE40 expression was confined to the cytoplasm, where it’s transcription activity would be suppressed." (PMID 32577154, 2020). "Furthermore, CU-DREAMX analysis demonstrated that BHLHE40 and DDIT4 of PBMCs were not increased in patients with head and neck cancers and pancreatic cancer." (PMID 34045534, 2021).
colon cancer (7 papers, 2019 to 2023). "NOTUM, which encodes for a palmitoleoyl-protein carboxylesterase being overexpressed in colon tumors and supporting tumor initiation and proliferation, was also found to be downregulated upon BHLHE40 ablation." (PMID 36890812, 2023). "An earlier study suggested that BHLHE40 is upregulated at both the mRNA and protein level in colon tumors, but this was based on a very small sample number of four." (PMID 36890812, 2023). "In colon cancer, BHLHE40 overexpression impeded serum deprivation-induced apoptosis and selectively inhibited the activation of procaspases related to the intrinsic death pathway (precaspase 3, 7, 9), without affecting the extrinsic death pathway." (PMID 32577154, 2020). "A recent study of human colon cancer identified a CD4+ TIL Th1 subset with elevated Bhlhe40 expression." (PMID 31801070, 2019). "Recently, several investigations indicated that BHLHE40 could enhance the malignant development of colon tumors by stimulating the HBEGF mechanism and the hypoxia signaling axis." (PMID 37773521, 2023). "To gain mechanistic insights how BHLHE40 could affect colon cancer cells, we performed RNA sequencing on HCT116 cells that expressed three different BHLHE40 shRNAs." (PMID 36890812, 2023). "While BHLHE40 levels were increased in colon cancer tissue compared to normal colon, cell cycle blockers markedly induced BHLHE40 expression." (PMID 32577154, 2020).
colorectal cancer (7 papers, 2020 to 2026). A primary or metastatic malignant neoplasm that affects the colon or rectum. "Previously, we performed RNA sequencing on ETV1-depleted human HCT116 colorectal cancer cells and found downregulation of BHLHE40 mRNA." (PMID 36890812, 2023). "OBJECTIVE: This study aimed to clarify how cancer-associated fibroblast-derived exosomal circ_0067557 (CAF-exo circ_0067557) promotes epithelial-mesenchymal transition (EMT) in colorectal cancer (CRC) through BHLHE40-mediated transcriptional activation of OTUB2." (PMID 42115880, 2026). "Interestingly, subsets of Th1-like CD4 T cells with high expression of Bhlhe40 were previously found to be enriched in patients with microsatellite instability colorectal cancer, who display favorable outcomes in response to anti-CTLA-477." (PMID 38187708, 2024). "Recently, Bhlhe40 was identified as a driver of EMT in colorectal cancer." (PMID 39062912, 2024). "Why BHLHE40 is upregulated in colorectal cancer has remained unknown, but our study strongly indicates that this could be due to enhanced activity of ETV1, JMJD1A and/or JMJD2A." (PMID 36890812, 2023). "BHLHE40 is a transcription factor, whose role in colorectal cancer has remained elusive." (PMID 36890812, 2023). "A significant example of this negative association is in colorectal carcinoma cells, where loss of BHLHE40 correlated with a high proliferation index, whereas BHLHE40 overexpression correlated with a low mitotic index." (PMID 32577154, 2020). "Subsequent studies described an alternate means by which BHLHE40 may suppress the growth of colorectal carcinoma." (PMID 32577154, 2020). "Therefore, BHLHE40 expression has a tumor suppressive effect in colorectal cancer." (PMID 32577154, 2020). "BHLHE40 downregulation suppressed both growth and clonogenic activity of human HCT116 colorectal cancer cells, strongly hinting at a pro-tumorigenic role of BHLHE40." (PMID 36890812, 2023). "Transcriptomic studies on human HCT116 colorectal cancer cells pointed at potential downstream effectors of ETV1, including the basic helix-loop-helix family member E40 (BHLHE40; also known as BHLHB2, DEC1, SHARP2 or STRA13)." (PMID 36890812, 2023). "BHLHE40 was identified as a target of TGF-β regulated Smad transcription in colorectal cancer, although it’s expression was independent of the growth inhibitory effects of TGF-β in these cells." (PMID 32577154, 2020). "Similarly, SNAI2, which encodes for a zinc-finger transcription factor regulating epithelial-mesenchymal transition and is overexpressed in colorectal tumors, was positively regulated by BHLHE40, and SNAI2 is capable of stimulating colorectal cancer cell invasion and tumor formation." (PMID 36890812, 2023).
glioma (7 papers, 2012 to 2025). A benign or malignant brain and spinal cord tumor that arises from glial cells (astrocytes, oligodendrocytes, ependymal cells). "A microarray expression analysis in mesenchymal gliomas found that expression of BHLHE40 and a number of other transcriptional regulators of mesenchymal transition including CEBPB, CEBPD, and STAT3 correlates with the extent of necrosis." (PMID 27096627, 2016). "Also, when looking at associations between genetic aberrations and expression in gliomas, the methylation state of RBP1 was reported to be associated with the expression of BHLHE40." (PMID 39941811, 2025). "Immunohistochemical analysis of 157 patients with newly diagnosed glioma and 63 with recurrent glioblastoma who relapsed during temozolomide (TMZ) chemotherapy showed that high BHLHE40 expression was significantly associated with high pathological tumor grade and poor response to TMZ." (PMID 32577154, 2020). "A subset of 7 transcription factors (STAT3, BHLHE40, CEBPA and B, RUNX1, FOSL2 and ZNF238) controlled most genes of the mesenchymal signature of gliomas; all but ZNF238 were significantly upregulated in the group 2 tumours compared to the other DIPG." (PMID 22389665, 2012). "The interaction between CCDC86 and BHLHE40 appears to be crucial for the transcriptional activation of ATF3, which may contribute to the oncogenic properties of glioma cells." (PMID 40837407, 2025). "Higher expression of BHLHE40 indicating worse prognosis in glioma, regardless of pathological subtype, which emphasized the potency of BHLHE40 as prognostic biomarkers in glioma and a putative biological function in brain tumor." (PMID 34224318, 2021). "BHLHE40 was upregulated in glioma compared to non-tumor brain tissue and played an oncogenic role in glioma cells." (PMID 32577154, 2020).
preeclampsia (7 papers, 2014 to 2025). Preeclampsia is a hypertensive disorder of pregnancy that is characterized by new-onset hypertension with proteinuria presenting after 20 weeks of gestation, and depending on mild or severe forms may initially present with severe headache, visual disturbances, and hyperreflexia. "Of note, candidate-gene approaches reported a lower methylation level of two genes, solute carrier family 2 member 1 (SLC2A1) and basic helix-loop-helix family member e40 (BHLHE40), in the placental tissue of pregnancies complicated by severe preeclampsia." (PMID 41361850, 2025). "Interestingly and in accordance with the role of hypoxia in preeclampsia, HIF1A can regulate the expression of several top DEGs identified in the meta-analysis including: LEP, FLT1, INHA, BHLHE40, SPAG4, HK2, HILPDA and ERO1L." (PMID 27802351, 2016).
autoimmune disease (6 papers, 2019 to 2025). A disorder resulting from loss of function or tissue destruction of an organ or multiple organs, arising from humoral or cellular immune responses of the individual to their own tissue constituents. "Moreover, BHLHE40 is overexpressed in anergic CD21low B cells of patients with hepatitis C virus, a subset recently underlined as pathogenic in autoimmune diseases." (PMID 35359922, 2022). "The protein basic helix-loop-helix family member e40 (BHLHE40) is a transcription factor recently emerged as a key regulator of host immunity to infections, autoimmune diseases and cancer." (PMID 38271477, 2024). "A principal function of Bhlhe40 in infectious and autoimmune disease models in mice is to suppress IL-10 expression in CD4+ T cells (17, –, 19, 22)." (PMID 37843306, 2023). "In autoimmune disorders, including colitis, experimental autoimmune encephalitis, and graft-versus-host disease, Bhlhe40 promotes pathology in mice." (PMID 37843306, 2023). "Satb1-mediated regulation of Bhlhe40 and PD-1 controls Th17 pathogenicity in part by IL-17 and GM-CSF production in the central nervous system during autoimmune disease." (PMID 30710091, 2019). "Given that immune-mediated protection requires a fine balance between pro-inflammatory response that limits pathogen replication and anti-inflammatory response that prevents immunopathology, Bhlhe40 emerges as a key player in host immune responses to infections, autoimmune disorders and cancer." (PMID 38271477, 2024). "Therefore, Bhlhe40 could be a pivotal transcriptional regulator for both antigen-specific and bystander MP CD4+ T cells in the context of CNS inflammation and targeting Bhlhe40 in CD4+ T cells may serve as a novel treatment strategy to control autoimmune diseases." (PMID 37121980, 2023). "In addition, Bhlhe40 seems to be required for Th1 and Th17 effector cytokine production, including IL-17A, GM-CSF and IFN-γ, in the context of autoimmune disease, GVHD, and Toxoplasma gondii infection models." (PMID 37121980, 2023).
diabetes (5 papers, 2018 to 2025). "In the present study, B12 modulated several core clock genes (Bmal1, Cry1, Cry2, Per1, Per3), while other genes were primarily affected by diabetes (Bhlhe40, Hif3a, and Nr1d1)." (PMID 41463345, 2025).
melanoma (5 papers, 2019 to 2025). A malignant, usually aggressive tumor composed of atypical, neoplastic melanocytes. "As a candidate transcription factor, a high level of BHLHE40 was reported to promote tumor progression in some cancers, like sarcomas, melanoma, lung, breast, colorectal and liver cancers." (PMID 37773521, 2023).
prostate carcinoma (5 papers, 2015 to 2024). A carcinoma that arises from epithelial cells of the prostate gland. "Some of the regulators affected by this treatment however could be implicated in anti-tumorigenic activities (i.e., IL-6), yet modulation identified in other regulators are potentially implicated in prostate cancer tumorigenesis, such as BHLHE40, and SRF." (PMID 38078010, 2023). "However, the role of BHLHE40 in SAL-induced cellular senescence in prostate cancer is poorly understood." (PMID 38902772, 2024). "Such a hypothesis gains credence considering the observation that TGF-β induces the upregulation of BHLHE40 and the downregulation of BHLHE41 in prostate cancer cells (PC-3)." (PMID 38067152, 2023).
breast tumors (4 papers, 2018 to 2026). "To determine whether BHLHE40-mediated expression of genes encoding cytokine or growth factors is relevant to clinical samples, we analyzed the mRNA expression data of breast tumors in The Cancer Genome Atlas (TCGA) database." (PMID 30285805, 2018). "BHLHE40 (basic helix-loop-helix family member e40) was also highly expressed in luminal A and luminal B breast tumor subtypes in TCGA, and showed a mild positive correlation with BRRIAR expression in these subtypes (Spearman’s r = 0.25, p = 7.08e-13)." (PMID 41501810, 2026). "Individuals carrying the protective 3p26 haplotype express BRRIAR in a subset of ER + breast tumors, where it maintains BHLHE40 and ISG expression and primes RIG-I for activation." (PMID 41501810, 2026). "We further examined the function of BHLHE40 in breast tumor cells with elevated baseline activation of HIF1A and BHLHE40 using the tamoxifen-resistant (TR) and fulvestrant-resistant (FR) variants of MCF7 cells." (PMID 30285805, 2018). "Among the cytokines and growth factors affected by BHLHE40-KD in LM cells, the expression level of HBEGF mRNA is positively correlated with the expression level of BHLHE40 mRNA in all four major subtypes of breast tumors in the TCGA database." (PMID 30285805, 2018). "The clinical relevance of our findings is evidenced by the fact that the elevated expression of BHLHE40 and HBEGF in breast tumors is associated with poor prognosis of patients with TNBC and chemoresistance." (PMID 30285805, 2018). "The expression of 71.4% (20 out of 28) of these BHLHE40-dependent genes was found to be positively correlated with BHLHE40 expression, with statistical significance (p < 0.05) in at least one of the four major subtypes of breast tumors." (PMID 30285805, 2018). "We provide evidence that BRRIAR regulates BHLHE40 in cis and binds to RIG-I in trans, modulating ER + breast tumor-intrinsic IFN signaling and promoting an IFN-driven immune response." (PMID 41501810, 2026). "In contrast, CLOCK, NPAS2, CIART/CHRONO, BHLHE40, RORA, and RORC were significantly up-regulated in these breast tumors." (PMID 38319971, 2024). "Conversely, individuals with the risk-associated 3p26 haplotype have absent or reduced expression of BRRIAR and BHLHE40 in a subset of ER + breast tumors, resulting in attenuated ISG transcription and increased tumor cell proliferation." (PMID 41501810, 2026).
hepatocellular carcinoma (4 papers, 2020 to 2021). A malignant tumor that arises from hepatocytes. "Other studies have noted that in hepatoma-derived cell lines, HIF-1α regulates the expression of BHLHE40." (PMID 32577154, 2020). "It has been shown that the basic helix-loop-helix (BHLH) transcription factor differentiated embryonic chondrocyte gene 1 (DEC1/BHLHE40/Stra13) is strongly expressed in oral, thyroid, breast, gastric and pancreatic cancers and in hepatocellular carcinoma cells compared to non-cancerous cells." (PMID 33089188, 2020).
Autoimmunity (3 papers, 2021 to 2024). The occurrence of an immune reaction against the organism's own cells or tissues. "For example, Bhlhe40-deficient mice developed lymphoid organ hyperplasia and autoimmunity with age." (PMID 36304536, 2022). "In Addition, BHLHE40 is emerging as a key regulator of immune response during autoimmunity and various inflammatory conditions." (PMID 34045534, 2021).
COVID-19 (3 papers, 2022 to 2025). A disease caused by infection with severe acute respiratory syndrome coronavirus 2. "DUSP6, BHLHE40, RASGRP1, and TAB2, the top 4 topological metric hub genes, appear to be pivotal molecular targets of COVID-19, AKI, and CKD." (PMID 37026010, 2023). "Hub genes identified from the protein–protein interaction (PPI) network, including DUSP6, BHLHE40, RASGRP1, and TAB2, are potential therapeutic targets in COVID-19 with AKI and CKD." (PMID 37026010, 2023).
endometrial cancer (3 papers, 2019 to 2024). Primary or metastatic malignant neoplasm involving the endometrium (mucous membrane that lines the endometrial cavity). "Knockdown of BHLHE40 in endometrial cancer cells resulted in suppressed oxygen consumption and enhanced extracellular acidification." (PMID 38301894, 2024). "In this study, we found that BHLHE40 expression was downregulated in cases of endometrial cancer of higher grade and advanced disease." (PMID 38301894, 2024). "BHLHE40 has been reported to be involved in the aggressiveness of various cancers, including colorectal, pancreatic, and endometrial cancers." (PMID 39872516, 2024). "In the present study, we showed that the expression levels of BHLHE40/41 were negatively correlated with those of the microRNA (MIR) 130 family in endometrial cancer (EC) specimens." (PMID 31384392, 2019). "Our immunohistochemical study showed that the expression of BHLHE40, PPM1F, and phosphorylated AMPKα correlated with the prognosis of endometrial cancer patients." (PMID 38301894, 2024).